KRT80 (keratin 80)
Diseases named in the same sentence as KRT80 in open-access papers (continued):
Sharing a sentence is not in itself a finding about the gene and the disease.
lung adenocarcinoma (6 papers, 2023 to 2025). A carcinoma that arises from the lung and is characterized by the presence of malignant glandular epithelial cells. "The association between KRT80 and lung adenocarcinoma disease progression was verified in Bulk transcriptome and single-cell transcriptome." (PMID 39247607, 2024). "In lung adenocarcinoma, KRT80 knockout has been reported to inhibit proliferation, suppressing the transition of cancer cells from the G1 to the S phase." (PMID 40647481, 2025). "A recent study showed that KRT80 is markedly overexpressed in lung adenocarcinoma, correlated with poorer patient outcomes and enhanced G1-to-S progression in lung cancer cell lines." (PMID 40647481, 2025). "For KRT80, which was differentially expressed in TB and lung adenocarcinoma, we found that with its elevated expression often predicted the occurrence of poor clinical staging." (PMID 39247607, 2024). "In addition, a recent study reported that KRT80 knockdown affected the cell cycle activity via CCND1 expression in lung adenocarcinoma cells." (PMID 40647481, 2025). "We further explored the expression of KRT80 in the differentiation trajectory and found that it was predominantly located in the Other type, which may suggest that KRT80 is involved in the malignant progression of lung adenocarcinoma tumors." (PMID 39247607, 2024). "In addition, KRT80 protein expression was found to be significantly higher in lung adenocarcinoma samples than in normal samples in the UALCAN database, while the level of KRT80 protein expression was elevated after alteration of Wnt pathway activity." (PMID 39247607, 2024). "Additionally, the interaction between KRT80 and VCP plays a crucial role in the progression of lung adenocarcinoma, which implies that KRT80 is a promising therapeutic target." (PMID 38495507, 2024). "KRT80 was found to have higher DNA methylation in grade 2 lung adenocarcinoma." (PMID 37211956, 2023). "The results showed that compared to BEAS-2B cells, KRT80, TRPA1, and C1QTNF6 were highly expressed in two lung adenocarcinoma cell lines (A549 and NCI-H1299)." (PMID 39247607, 2024).
lung carcinoma (5 papers, 2019 to 2025). "In the current work, we found that KRT80 was elevated in lung cancer, and depletion of KRT80 repressed the proliferation and invasion of NSCLC cells." (PMID 36248424, 2022). "ENCODE TFs mapping showed that SREBP1 can bind the core-E1 enhancers in lung cancer cells, the only ENCODE profiled cells characterized by strong KRT80 transcription." (PMID 31073170, 2019). "GSEA analysis demonstrated that KRT80 was enriched in the PI3K/AKT pathway, a well-established therapeutic target in lung cancer." (PMID 38495507, 2024).
colon cancer (4 papers, 2019 to 2025). "In order to characterize the in vitro effectiveness of miR-195-5p on KRT80 expression, we performed transient transfection with miR-195-5p mimic molecules in the human colonic cancer cells, HCT116 and HT29." (PMID 40647481, 2025). "Moreover, other studies have reported that circular RNAs or lncRNAs modulate KRT80 expression via sponging miRNAs in gastric and colon cancers, reinforcing the broader relevance of the post-transcriptional regulation of KRT80 in epithelial tumors." (PMID 40647481, 2025). "LINC01485 targeting miR-383-5p/KRT80 promoted colon cancer proliferation." (PMID 38495507, 2024). "The TCGA results indicated that SPIB, KRT24, PHLPP2, PLP1, BEST4, CA7, and C11orf86 were all downregulated, while KRT80, SLC39A10, AJUBA, FOXQ1, and CLDN1 exhibited upregulated levels in colon cancer." (PMID 32633726, 2020).
esophageal squamous cell carcinoma (3 papers, 2021 to 2025). Esophageal squamous cell carcinoma (ESCC) is a type of esophageal carcinoma (EC) that can affect any part of the esophagus, but is usually located in the upper or middle third. "Additional studies further support the oncogenic properties of KRT80 in terms of tumor biology; for instance, in esophageal squamous cell carcinoma, KRT80 overexpression enhances proliferation, invasiveness, and lymph node metastasis." (PMID 40647481, 2025).
lymph node metastasis (3 papers, 2021 to 2023). "An analysis of 102 OC patients revealed a significant correlation between KRT80 expression and FIGO stage and lymph node metastasis, i.e., higher KRT80 expression was correlated with a later FIGO stage and a higher rate of lymph node metastasis." (PMID 37211956, 2023). "A high expression rate of KRT80 was significantly correlated with FIGO stage and lymph node metastasis (P < 0.01)." (PMID 34659572, 2021). "The positive rate of KRT80 in the lymph node metastasis group (81.82%) was higher than that in non-metastasis group (44.62%)." (PMID 34659572, 2021). "The positive expression rate of KRT80 was related to FIGO stage and lymph node metastasis, but not to the age, histological grade, and pathological type of the patient." (PMID 34659572, 2021).
prostate carcinoma (3 papers, 2022 to 2025). A carcinoma that arises from epithelial cells of the prostate gland. "Conversely, in the other study, KRT8, KRT15, KRT19, KRT34, and KRT80 were found to be enriched in African American prostate cancer samples." (PMID 40104216, 2025). "An earlier study showed KRT80, RUNX, GATA6, SERPINB13, and SLC6a14 are important markers for prostate cancer progression, whereas we also identified KRT80, RUNX as well as GATA2, GATA2-AS1 in our study." (PMID 37476073, 2023). "KRT34 and KRT80 expression levels were too low or were hardly detected in all the prostate cancer cell lines (Data not shown)." (PMID 36033462, 2022).
esophageal cancer (2 papers, 2024 to 2025). A primary or metastatic malignant neoplasm involving the esophagus. "High KRT80 expression in esophageal cancer has been shown to exacerbate invasive phenotypes and contribute to chemotherapy resistance." (PMID 40428339, 2025). "Here, KRT80 mRNA expression was found to be higher in esophageal cancer than normal epithelium by RT-PCR and bioinformatics analysis (p < .05), opposite to KRT80 methylation (p < .05)." (PMID 38241178, 2024). "There was a negative relationship between promoter methylation and expression level of KRT80 gene in esophageal cancer (p < .05)." (PMID 38241178, 2024). "Here, we for the first time clarified the clinicopathological significances and related molecular mechanisms of KRT80 expression in esophageal cancer." (PMID 38241178, 2024). "KRT80 mRNA expression was positively correlated with the differentiation, infiltration of immune cells, and poor prognosis of esophageal cancer (p < .05)." (PMID 38241178, 2024). "In summary, KRT80 is believed to be involved in the pathogenesis and subsequent progression of esophageal cancer by promoting anti-apoptosis, anti-pyroptosis, migration, invasion, and EMT of esophageal cancer cells." (PMID 38241178, 2024). "Immunohistochemically, KRT80 protein was positively expressed in esophageal squamous epithelial cells and esophageal cancer cells." (PMID 38241178, 2024). "We found a higher expression of KRT80 mRNA in the cancer than normal epithelium of esophagus by xiantao database (p < .05), and positively related to adenocarcinoma subtype of esophageal cancer by UALCAN database (p < .05)." (PMID 38241178, 2024). "KRT80 mRNA expression was positively linked to no infiltration of immune cells, the short survival time of esophageal cancers (p < .05)." (PMID 38241178, 2024). "KRT80 knockdown suppressed anti-apoptosis, anti-pyroptosis, migration, invasion, chemoresistance, and lipogenesis in esophageal cancer cells (p < .05), while ACC1 and ACLY overexpression reversed the inhibitory effects of KRT80 on lipogenesis and chemoresistance." (PMID 38241178, 2024). "KRT80 silencing reduced the expression of MMP-9, which account for the promoting effects of KRT80 on the invasion and metastasis of esophageal cancer cells." (PMID 38241178, 2024). "Considering the frequency and density, KRT80 expression was stronger in young than elder cancer patients (p < .05), but not correlated with sex, histological grade, T stage, N stage or AJCC staging of esophageal cancers (p > .05)." (PMID 38241178, 2024). "There was a negative relationship between KRT80 mRNA and methylation (cg01182683) in esophageal cancer (p < .05) in terms of xiantao database." (PMID 38241178, 2024). "KRT80 might induce the chemoresistance by lipid droplet assembly and ACC1- and ACLY-mediated lipogenesis in esophageal cancer cells." (PMID 38241178, 2024).
keratoconus (2 papers, 2022 to 2025). A degenerative, structural disorder of the eye, characterized by a cone-shaped protrusion of the cornea. "Immunohistochemical staining of KRT80 confirmed the hyper-differentiation signal of corneal superficial layer in keratoconus." (PMID 35821117, 2022). "Among these genes, a highly and specifically expressed gene in keratoconus CSfCs, KRT80, which was related to advanced tissue or cell differentiation." (PMID 35821117, 2022).
hepatocellular carcinoma (1 paper, 2025). A malignant tumor that arises from hepatocytes. "A higher expression of KRT80 has also been correlated with the promotion of the epithelial–mesenchymal transition in hepatocellular carcinoma (HCC) cell lines, affecting the PI3K/AKT signaling pathway." (PMID 40647481, 2025). "Recent evidence shows that KRT80 is aberrantly expressed in a variety of malignancies, including colorectal, gastric, lung, ovarian, and hepatocellular carcinomas." (PMID 40647481, 2025). "In hepatocellular carcinoma, KRT80 functions as an oncogene, influencing the epithelial–mesenchymal transition and modulating the PI3K/AKT signaling pathway, thereby contributing to tumor progression." (PMID 40647481, 2025).
Pleural effusion (1 paper, 2019). The presence of an excessive amount of fluid in the pleural cavity. "Interestingly, KRT80 positivity strongly characterized invading cells from prospectively collected pleural effusion from AI-treated patients 33,34." (PMID 31073170, 2019).
thyroid carcinoma (1 paper, 2022). "Analysis from the online site UALCAN displayed that KRT80 was a positive correlation with TGFBR1 in adrenocortical carcinoma (ACC), kidney renal papillary cell carcinoma (KIRP), and thyroid carcinoma (THCA), and their Pearson Correlation Coefficient was 0.37, 0.34, and 0.3." (PMID 36248424, 2022).
tumor (23 papers, 2018 to 2025). "Although KRT80 may act as a mediator of oncogenic signaling with a potential impact on tumor behavior, the precise molecular mechanisms underlying its contribution to CRC development require further investigation." (PMID 40647481, 2025). "This is consistent with the altered protein expression of KRT80 in response to altered Wnt pathway activity, i.e., KRT80 is associated with tumor metastasis and may act through the Wnt pathway." (PMID 39247607, 2024). "By analyzing the relationship between clinical features and KRT80 expression, we found that KRT80 expression varied in different pathological stages, and KRT80 expression increased with increasing stage, which may predict that KRT80 is associated with tumor metastatic progression." (PMID 39247607, 2024). "Although the expression patterns of KRT80 and KRT78 appear similar, a closer examination reveals that KRT80 exhibits a thicker band of expression on the left, specifically within the tumor regions." (PMID 40236135, 2025). "Notable examples within this intersecting group of genes included CDH3, ETV4, ESM1, and KRT80, all previously implicated in CRC progression and tumor microenvironment modulation." (PMID 40722723, 2025). "This demonstrated that the loss of function of KRT80 affected the cell cycle activity, inhibiting the transition of CRC cells from the G1 phase to the S phase and, hence, tumor growth." (PMID 40647481, 2025). "The overexpression of KRT80 in these cancers has been correlated with more aggressive tumor phenotypes, higher rates of proliferation, enhanced migratory and invasive capabilities, and poorer clinical outcomes." (PMID 40647481, 2025). "Combining results from bioinformatics analysis and clinical samples, we observed that the high KRT80 group had a shorter survival period, suggesting a link between KRT80 expression and tumor progression." (PMID 38495507, 2024). "The inverse correlation between the A947 concentrations and transcriptional target gene (KRT80) biomarker representing SMARCA2 levels were demonstrated in tumor tissues." (PMID 38755248, 2024). "In many neoplastic diseases, the high expression status of KRT80 and its role in regulating the biological functions of cancer cells have been well established." (PMID 37211956, 2023). "KRT80 is overexpressed in many neoplasms and plays an essential role in promoting cell proliferation, migration and invasiveness, and is associated with poor prognosis in cancer patients." (PMID 37211956, 2023). "In particular, in molecularly targeted cancer therapy, targeted inhibition of the KRT80 gene, thereby attenuating the proliferation, invasion and metastatic ability of tumor cells and improving patient prognosis, is a promising potential therapeutic approach." (PMID 37211956, 2023). "In this review, we summarize the basic facts about the keratin family and KRT80, the essential role of KRT80 in neoplasms, and its potential as a therapeutic target." (PMID 37211956, 2023). "In recent years, numerous studies have shown that KRT80 regulates biological functions and patient prognosis in neoplasms." (PMID 37211956, 2023). "The relationship between KRT80 and neoplasms has been studied extensively, particularly in gastrointestinal tumors such as GC." (PMID 37211956, 2023). "In neoplastic diseases, KRT80 is overexpressed in many cancers and plays an essential role in promoting proliferation, migration, invasiveness and poor prognosis." (PMID 37211956, 2023). "Xenograft tumor experiments showed that depletion of KRT80 attenuated xenograft tumor growth in mice." (PMID 36248424, 2022). "More importantly, through high-throughput transcriptome analysis (RNA-seq, in NODE database, OEZ007550), we identified KRT80, a tumor suppressor in HNSC, as the target of HNSCAT1." (PMID 35965679, 2022). "Amassing evidence recommends that KRT80 is abnormally communicated in tumor tissues and is correlated with tumor progression." (PMID 36248424, 2022).
tumor (continued). "Although the mechanism of KRT80 regulating tumor progression has been gradually reported, the mechanism of KRT80 in NSCLC is still unclear and worth exploring." (PMID 36248424, 2022). "A total of 33 tumor samples (82.5%) showed higher KRT80 expression in CRC tissues as compared with paired normal mucosa, with 28 tumor samples (70%) having at least a twofold increase." (PMID 30262880, 2018). "Additionally, the critical oncogenic properties of KRT80 were demonstrated, both siRNA- and miR-195-5p mediated KRT80 repression, impairing tumor growth by inhibiting cell cycle progression." (PMID 40647481, 2025). "Additionally, the critical oncogenic properties of KRT80 were demonstrated that, once silenced, suppressed tumor growth." (PMID 40647481, 2025). "To explore more detailed biochemical alterations, we obtained the Reactome gene set and performed enrichment analysis, which showed that epithelial-mesenchymal transition, Wnt pathway, and tumor cell division-related pathway were highly active in the KRT80 high expression group." (PMID 39247607, 2024). "We found a significant amplification of KRT80-ChgA dual-positive cells, indicating that these rare cells in non-tumoral ovarian tissues could be the progenitors that expand to form the tumor mass (upper block of IHC pictures, OR E–H)." (PMID 39592661, 2024). "This upregulation of KRT80 promotes tumor stiffness and cancer invasion." (PMID 39358487, 2024). "Due to the widespread expression of KRT80 in epithelial cells and its many unique properties, researchers have been investigating its role in disease, particularly in neoplasms, including its effects on the biological functions of cancer cells, mechanisms, and patient prognosis." (PMID 37211956, 2023). "Moreover, depletion of KRT80 attenuated xenograft tumor growth and the expressions of KRT80, Ki-67, and TGFBR1." (PMID 36248424, 2022). "Conclusively, our study demonstrated that the lncRNA HNSCAT1/miR-1245/KRT80 axis functions as a necessary tumor-suppressive signaling pathway in HNSC, which highlights a novel mechanism of lncRNA function and provides alternative targets for the diagnosis and treatment of HNSC." (PMID 35965679, 2022). "KRT80 promotes tumor progression by activating the AKT signaling pathway." (PMID 34659572, 2021). "In addition, transcription factors are involved in the regulation of KRT80 expression during tumor progression." (PMID 34659572, 2021). "Interestingly, meta-analysis of tumor and matched nearby tissue from TCGA show increased KRT80 mRNA in the tumor biopsies." (PMID 31073170, 2019). "Patients with KRT80-positive tumor staining had shorter DFS and OS." (PMID 30262880, 2018). "Similarly, multiple reports have indicated that KRT80 promotes tumor progression." (PMID 38495507, 2024). "KRT80 may have far‐reaching effects on the human body, and this marker may play a crucial role in the function of cancer cells and the prognosis of cancer patients, so it has a promising future in the field of neoplasms." (PMID 37211956, 2023). "In addition, KRT80 can distinguish CRC tumors from normal tissues and the phenotype of MSS from MS‐H, which is associated with the tumor microenvironment and the efficacy of immune checkpoint therapy in CRC, making KRT80 a potentially important biomarker for CRC." (PMID 37211956, 2023). "Also, KRT80 staining increased with the increase in tumor grade." (PMID 30262880, 2018). "In this regard, dosing every 2 weeks at 40 mg/kg still showed sustained tumor growth inhibition that was similar to 40 mg/kg dosed weekly, with comparable effects on the pharmacodynamic biomarkers SMARCA2 and KRT80 mRNA." (PMID 38755248, 2024). "KRT80 expression was modulated by lncRNA HNSCAT1 and presented a positive correlation in tumor samples (R = 0.52, p < 0.001)." (PMID 35965679, 2022).